LENG9 (leukocyte receptor cluster member 9)
Gene: Protein-coding gene on chromosome 19 (54,461,732 to 54,463,778, reverse strand). Ensembl gene ENSG00000275183.
Subcellular location (Human Protein Atlas): Nucleoli fibrillar center
Genetic constraint (gnomAD): Loss-of-function variants: 0 observed, 0.48 expected, observed/expected ratio (o/e) 0, 90% interval 0 to 1.84. That is too few expected variants to judge how well the gene tolerates losing a copy. Missense variants: 872 observed, 578.59 expected, observed/expected ratio (o/e) 1.51, 90% interval 1.42 to 1.59. Synonymous variants: 410 observed, 277.43 expected, observed/expected ratio (o/e) 1.48, 90% interval 1.36 to 1.6.
Homologues: Orthologues: chimpanzee LENG9 (97% identical), pig LENG9 (60% identical), rat Leng9 (57% identical), mouse Leng9 (56% identical), tropical clawed frog leng9 (29% identical), zebrafish leng9 (16% identical). Paralogues in human: NUP42 (13% identical).
Diseases named in the same sentence as LENG9 in open-access papers:
LENG9 is named in the same sentence as 4 diseases in open-access papers, as found by Europe PMC text mining. Sharing a sentence is not in itself a finding about the gene and the disease. The quoted sentences say what the papers report.
cervical cancer (1 paper, 2022). A primary or metastatic malignant neoplasm involving the cervix. "Combined with the corresponding RNA-seq data, we highlighted LINC00290, LINC02500, and LENG9 as potential driver genes in cervical cancer." (PMID 35538075, 2022). "We further highlighted LINC00290, LINC02500, and LENG9 as potential driver genes in cervical cancer." (PMID 35538075, 2022). "Combining this with the corresponding RNA-seq data, we were able to pinpoint LINC00290, LINC02500, and LENG9 as potential driver genes in cervical cancer." (PMID 35538075, 2022). "Combined with the corresponding RNA-seq data, we highlight LINC00290, LINC02500, and LENG9 as potential driver genes for cervical cancer." (PMID 35538075, 2022). "To evaluate the potential functional role of LENG9 in cervical carcinoma, we overexpressed LENG9 in cervical cancer cell lines CaSki and SiHa, as LENG9 expression was significantly upregulated in HPV-integrated cervical tumors (i.e., ZLR-08)." (PMID 35538075, 2022). "Combined with the corresponding RNA-seq data, we highlight LINC00290, LINC02500 and LENG9 as potential driver genes in cervical cancer." (PMID 35538075, 2022). "Their interactions with LENG9 may be a potential mechanism underlying the promotion of cell proliferation and migration when LENG9 is upregulated in cervical cancer cells while these warrant further functional investigation in the future." (PMID 35538075, 2022). "Most of these genes have been reported to be associated with cancer, while LENG9 is rarely reported in the literature and has not been implicated in cancer, suggesting that LENG9 may be a potential tumor driver gene in cervical cancer." (PMID 35538075, 2022).
cervical tumors (1 paper, 2022). "In particular, it was observed that only the gene LENG9 was completely amplified in this target region, resulting in its highest expression among all 103 cervical tumors." (PMID 35538075, 2022).
tumor (1 paper, 2022). "Taken together, these results suggest that LENG9 may play an oncogenic role in tumor pathogenesis by promoting tumor cell proliferation, migration, and invasion." (PMID 35538075, 2022).
LENG9 also shares sentences with these, for which no sentence is quoted: cancer (1 paper).